IL15 (interleukin 15)
Diseases named in the same sentence as IL15 in open-access papers (continued):
Sharing a sentence is not in itself a finding about the gene and the disease.
influenza (continued). "This biased expression of CD122/132 receptor chains over IL-15Rα and enhanced IL-15 levels following influenza infection, indicate that NK cells accumulating at the site of influenza infection are capable of responding to locally produced IL-15 via the trans-presentation pathway." (PMID 22624047, 2012). "Therefore, future work is needed to identify the IL-15-producing cell population(s) and the mechanism of migration to this cytokine in order to target this response for eventual applications in influenza vaccines and treatments." (PMID 22624047, 2012). "Following influenza infection, the IL-15-producing cell type(s) is/are still unknown, but influenza-induced expression of IL-15 is clearly an important regulator of the NK and CD8 T cell responses to this virus." (PMID 22624047, 2012). "Therefore, we monitored the influx of NK cells in animals receiving either PBS or anti-IL-15 mAb administered i.p. daily from day 0 through day 4 post influenza infection." (PMID 22624047, 2012). "Therefore, these combined data indicate that influenza-induced IL-15 is an important signal for the migration of NK cells to the lung airways where they help limit viral replication." (PMID 22624047, 2012). "Although dendritic cells are known to be an important source of IL-15 at day 6 post influenza infection, it is unclear whether DCs or other cell types produce IL-15 to facilitate specific immune responses to influenza." (PMID 22624047, 2012). "Together this work suggests that local deposits of IL-15 in the lung airways regulate the coordinated innate and adaptive immune responses to influenza infection and may represent an important point of immune intervention." (PMID 22624047, 2012). "However, Type I IFNs also modulate the expression of the common gamma chain cytokine interleukin 15 (IL-15), which we recently reported to be temporally and locally increased following influenza infection." (PMID 22624047, 2012). "We thus hypothesized that IL-15 was important for the migration of NK cells in the lung airways following influenza infection." (PMID 22624047, 2012). "As IL-15 deficiencies also cause reductions in CD8 T cell accumulation in the BAL, chemotactic potential of IL-15 for NK cells presented here provides a possible link between IL-15-mediated effects of both the innate and adaptive immune responses to influenza infection." (PMID 22624047, 2012). "Finally, acute influenza infection was associated with low plasma concentrations of inflammatory cytokines, including IFN-γ, MIP-1β, IL-2 and IL-15, and high levels of the anti-inflammatory cytokines IL-10 and IL-1ra." (PMID 21966414, 2011). "Early secretion of Th17 (IL-8, IL-9, IL-17, IL-6) and Th1 cytokines (TNF-α, IL-15, IL-12p70) were detected in severe influenza patients, which were involved in cell-mediated immunity, may be associated with pathogenesis and autoimmune diseases induced by influenza." (PMID 40248710, 2025). "However, the consistent negative association of IL-15 with antibody response in both the discovery and replication cohort suggests a detrimental role in protection against influenza." (PMID 39331702, 2024). "Because this IL-15 expression was rapidly induced by influenza infection and reached significant levels as early as day 3 post infection (p.i.), we hypothesized that influenza-induced IL-15 expression may be an important mediator of NK cell responses to influenza infection." (PMID 22624047, 2012). "IL-15 boosts NK cell responses to influenza viruses, while IFN-γ-producing NK cells can be induced following influenza vaccination." (PMID 40881708, 2025). "The cooperation of these two signaling pathways (IL-7 and IL-15 signaling) supported the residence of CD4+ TSCMs in the bone marrow and the recalling of CD4+ TSCMs in the influenza model." (PMID 30733641, 2019).
influenza (continued). "Besides, another study showed that high dose of plasmid-encoded IL-15 could even inhibit the immune response of an influenza DNA vaccine suggesting that high levels of IL-15 activity might not have the desired effect for different vaccination strategies." (PMID 30452438, 2018). "Our results suggest that the stimulation of B cellsin vitro with inactivated H3 influenza in combination with CpG2006 ODN and IL-15 not only stimulate increased anti-HA IgG, but appears to increase levels of secreted cross-reactive IgG compared with CpG alone." (PMID 29479423, 2017). "Co-administration of IL12 and influenza subunit vaccine to newborn mice led to increased splenic expression of IFNγ, IL10 and IL15 mRNA and enhanced protective efficacy of antiviral immunisation." (PMID 29124321, 2017). "We currently favor a model in which NK cells migrate directly to influenza-induced IL-15 in the lung airways, and, CD8 T cell trafficking, in turn, occurs to both IL-15 directly and to chemotactic factors produced by NK cells already present at the site." (PMID 22624047, 2012). "Their results underscored the effectiveness of this multivalent formulation (Wyeth/IL-15/5Flu) as a broad-spectrum influenza vaccine, generating protective immunity irrespective of neutralizing antibody involvement." (PMID 41196843, 2025). "IL-15 has previously been identified to support the generation of superior, lung-resident antiviral CD4 + T cells with the ability to protect against lethal influenza infection in mice." (PMID 39030218, 2024). "Abnormalities in IL-15, NCR1, CD27, and an increase in T & NK cell activation traits, similar to those observed during swine flu and influenza, were prominent and may be considered a target of further investigation using a more controlled methodology." (PMID 34177897, 2021). "In addition, hsa-miR-326, hsa-miR-15b-5p, hsa-miR-885, hsa-miR-122-5p, hsa-miR-133a-3p, and hsa-miR-150-5p showed high correlations to IL-6, IL-15, IL-17A, IL-1β, and monocyte chemoattractant protein-1 (MCP-1) with both strains of influenza." (PMID 33540650, 2021). "Several cytokines, including type I IFNs, IL-12, IL-15 and IL-18 are known to be important for NK cell activity against viral pathogens, but their roles during influenza infection specifically are not clear." (PMID 23300570, 2012). "The studies presented here emphasize the importance of IL-15 in mediating the innate response to influenza via the trafficking of NK cells, as viral titers were not as efficiently controlled early after infection in IL-15-blocked animals." (PMID 22624047, 2012). "IL-7 and IL-15 are critical for memory CD8+ T-cell homeostasis 9–11, and expression of IL-7R and IL-15R by NP-specific CD8+ T cells was comparable at 2 and 6 months after influenza infection." (PMID 22965681, 2012). "For instance, IL-15 prolongs the survival of effector T cells against Listeria monocytogenes and Mycobacterium bovis and augments the response by respiratory CD8+ T cells in Influenza infections." (PMID 23028916, 2012). "Regardless of mechanism, IL-15-induced trafficking of lymphocytes is an important part of our overall understanding of influenza immunobiology." (PMID 22624047, 2012). "In conclusion, plasma chemokines and cytokine levels prior to or in the first few days post-influenza vaccination may be predictive of serological responses to vaccination, with changes in IFN-γ, IL-17A, and IL-15 post-vaccination possibly indicative of the activation of cell-mediated immunity." (PMID 40881708, 2025). "For instance, IL-15 knockout mice exhibit reduced mortality despite unchanged viral titers as a result of diminished CD8+ T cell-mediated lung injury rather than impaired influenza control." (PMID 40872830, 2025). "For instance, during acute influenza infection, lung CD8+ T cells lack CD25 expression and proliferate nonspecifically, driven by inflammatory cytokines like IL-15 but plays a limited role in viral clearance." (PMID 40872830, 2025).
influenza (continued). "Mice were vaccinated twice 21 days apart with phosphate-buffered saline (PBS), seasonal quadrivalent inactivated influenza vaccine (S-QIIV), or Wyeth/IL-15/5Flu and infected with a nonlethal dose of IAV (H1N1)." (PMID 35385318, 2022). "Another report concluded that TSLP enhances CD8+ T-cell responses during primary influenza infection, but that this was not due to a direct action on CD8+ T cells and instead was an indirect effect on CD8+ T-cell responses resulting from TSLP-induced IL-15 production by dendritic cells." (PMID 33439121, 2021).
sarcopenia (47 papers, 2012 to 2025). Progressive decline in muscle mass due to aging which results in decreased functional capacity of muscles. "Some studies revealed a significant relationship between myokine and phenotype of sarcopenia and/or physical frailty, such as myostatin and IL-15 associated with muscle weakness and/or wasting, IGF-1 with muscle weakness, slowness, disability." (PMID 38375321, 2024). "One study found IL-15 to be a promising treatment for muscle loss under cachexia and sarcopenia conditioning." (PMID 35250869, 2022). "A key mechanism underlying the impaired immunity in individuals with sarcopenia refers to the abnormal myokines, such as interleukin (IL)‐15, IL‐17, and IL‐6." (PMID 34541518, 2022). "Together with the finding that low levels of plasma IL-15 associate with sarcopenia in old people, these results highlight IL-15 as an interesting therapeutic target for sarcopenia." (PMID 36499366, 2022). "Multivariate analysis showed that lower IL-15 levels were independently associated with sarcopenia, along with age and body mass index, suggesting that reduced IL-15 may be an indicator of age-related muscle loss." (PMID 40944148, 2025). "Several additional scenarios may contribute to IL-15 downregulation: mismatched exercise intensity and dietary intake, short or irregular training durations, underlying pathologies such as sarcopenia or metabolic syndrome, or chronic maladaptation to exercise." (PMID 40725674, 2025). "Additionally, IL-15 can reduce the accumulation of adipose tissue and improve intramuscular fat infiltration, which is beneficial for preventing and delaying sarcopenia caused by aging or disease." (PMID 41140691, 2025). "Moreover, in the multivariate regression analysis, plasma IL-15 levels were found to be independently and inversely associated with sarcopenia." (PMID 38032288, 2023). "IL-15 serum levels decrease in older people with loss of muscle mass, which suggested that sarcopenia may lead to immune function impaired." (PMID 35923193, 2022). "Decreased plasma IL-15 levels are associated with sarcopenia." (PMID 35250869, 2022). "On the other skeletal muscle aging and sarcopenia are associated with low levels of IL-15." (PMID 30283350, 2018). "Thereby, decreased interleukin-15 and increased adipokines levels might be associated with the interaction between sarcopenia and immune depression." (PMID 28549466, 2017). "Serum interleukin-15 levels decrease in older adults with the loss of muscle mass, suggesting that muscle loss may lead to impaired immune function, which may have some relevance to sarcopenia." (PMID 36969820, 2023). "Sarcopenia itself may develop as a result of aging, catabolic disorders, cancer, and deficient nutrition, as well as impeded host immune activity through suppressed production of IL-15." (PMID 32770952, 2020). "In the context of aging, a human observational study involving 123 community-dwelling older adults showed that plasma IL-15 concentrations were significantly lower in individuals with sarcopenia compared to controls (p < 0.001)." (PMID 40944148, 2025). "IL-15 levels tend to decline with aging, contributing to the metabolic and structural deterioration seen in sarcopenia." (PMID 41441428, 2025). "After exercise, the secretion of IL-15 increases, making it one of the key molecular mechanisms through which exercise combats sarcopenia." (PMID 41140691, 2025). "In addition, several studies have demonstrated that sarcopenia was associated with insulin resistance, vitamin D deficiency, elevated levels of inflammatory cytokines (such as tumor necrosis factor-alpha and interleukin-6), and decreased concentrations of muscle factors (such as interleukin-15)." (PMID 38287345, 2024). "Previous studies have shown that pro-inflammatory biomarkers, including IL-6, IL-10, IL-8, IL-15, CRP, TNF-α, and GDF-15, are associated with skeletal muscle decline and sarcopenia." (PMID 38026977, 2023).
sarcopenia (continued). "Concomitantly, the results from an outpatient study with 160 participants found a correlation between low levels of plasma IL-15 and sarcopenia." (PMID 37887382, 2023). "Skeletal muscle tissue produces myokines, such as interleukin (IL)-6, IL-15, tumor necrosis factor-α, and transforming growth factor-β, and altered myokine activity can induce immune senescence in sarcopenia." (PMID 37958368, 2023). "We assumed that the reduction in lean mass due to sarcopenia leads to lower levels of IL-15 and therefore NK cells." (PMID 37509255, 2023). "Understanding the complete relationship between NK function, IL-15, sarcopenia, and PD is a very intriguing and complicated challenge." (PMID 37509255, 2023). "A study involving 160 older adults provided insights into our results, demonstrating that control subjects had significantly higher levels of IL-15 compared to individuals with sarcopenia." (PMID 38032288, 2023). "Sarcopenia is a reason for the impaired immunity because of the presence of IL-6, IL-15, IL-17, myokines that are responsible for the proliferation and function of the immune system." (PMID 36143878, 2022). "Regarding the pathogenesis of sarcopenia, Sakuma and Yamaguchi have suggested in their review that IL-15 levels are low in individuals with sarcopenia and that its levels gradually decline with aging." (PMID 36362238, 2022). "People with sarcopenia have reduced interleukin-15, which has an effect on the immune system, especially on natural killer cells." (PMID 36090356, 2022). "They suggested that decreased IL‐15 levels during aging constitute a common mechanism for sarcopenia and immune senescence." (PMID 36091309, 2022). "Taken together, the literature supports a muscle-sparing effect of IL-15, particularly in conditions of dysregulated protein turnover such as cancer cachexia and possibly sarcopenia, through the suppression of muscle protein catabolism." (PMID 33528828, 2021). "Elderly subjects with sarcopenia have significantly lower plasma IL-15 levels, and studies have reported a relationship between sarcopenia and insufficient plasma IL-15 levels." (PMID 33019579, 2020). "A cross‐sectional study showed that there was a negative relationship between IL‐15 levels and sarcopenia risk in older people." (PMID 39764565, 2025). "These alterations may weaken the beneficial effects of IL‐15 signaling and decrease the ratio of muscle to fat content, resulting in sarcopenia." (PMID 39764565, 2025). "Together, these findings suggest that sarcopenia may undermine the effectiveness of immune checkpoint inhibitors by disrupting the IL-15/IL-6 balance and exacerbating T-cell dysfunction." (PMID 41019539, 2025). "Thus, IL-15 can be one of the beneficial factors during sarcopenia treatment related to advanced aging." (PMID 38397196, 2024). "In contrast to the role of IL15 in sarcopenia, some evidence suggests that IL15 could promote the activation of osteoclasts, thus contributing to bone resorption and BMD loss during osteoporosis." (PMID 38892069, 2024). "The level of IL-15 could be a potential contributor to exercise benefits in sarcopenia and cognitive function improvement." (PMID 37577356, 2023). "Previous study showed that IL-15 levels decrease in older people with sarcopenia, which suggested that sarcopenia may lead to immune function impaired." (PMID 37872469, 2023). "During aging, the level of IL-15 in skeletal muscle decreases as shown in a cross-sectional study with 160 outpatient elderly people which demonstrated the inverse correlation between plasma IL-15 levels and sarcopenia." (PMID 37577356, 2023). "This suggests that a lower level of IL-15 could impair the anabolic effects on skeletal muscles and hinder myoblast differentiation, potentially leading to the development of sarcopenia." (PMID 38032288, 2023). "IL-15 levels are significantly higher in controls compared to sarcopenia." (PMID 35250869, 2022).
sarcopenia (continued). "Studies in murine cell lines and in mouse models suggest that IL-15 promotes myogenesis and may protect against the inflammation-mediated skeletal muscle atrophy which occurs in sarcopenia and cachexia." (PMID 29021612, 2017). "Furthermore, mRNA levels of interleukin-15 (IL-15) are known to increase significantly with age and under limb unloading conditions in experimental models, suggesting its involvement in the muscle atrophy and cellular senescence characterizing sarcopenia." (PMID 40564069, 2025). "Tumor necrotizing factor (TNF)-α, interleukin (IL)-1β, IL-6, and IL-15 levels were assessed at baseline for both groups and after a 12-week intervention consisting of resistive exercise and supplementation with branched-chain amino acids, calcium, and vitamin D3 in the patients with sarcopenia." (PMID 38032288, 2023). "Impaired IL-15 signaling may contribute to the coalescence of sarcopenia and obesity." (PMID 37887382, 2023). "However, if confirmed by larger studies, the connection between NK function, IL-15, sarcopenia, and tumor progression may suggest some interesting perspectives." (PMID 37509255, 2023). "Given the propensity of the elderly to develop sarcopenia, we hypothesised that myogenic cultures derived from the skeletal muscle of elderly individuals would be more resistant to the hypertrophic effects of IL-15 than those of young individuals." (PMID 29021612, 2017). "Currently, both IL-10 and IL-15 are primarily used in research settings and are not part of routine clinical assessments for sarcopenia." (PMID 41441428, 2025). "We proved that basal NK levels were reduced in patients with sarcopenia, but IL-15 levels were not different." (PMID 37509255, 2023). "The GEE analysis adjusted by age and gender revealed sarcopenia significantly elevated TNF-α (p=0.003), IL-1β (p=0.001) and IL-6 (p<0.001), whereas intervention led to a decrease in TNF-α (p=0.005) and IL-1β (p=0.017) and an increase in IL-15 (p=0.024)." (PMID 38032288, 2023). "The average levels of the four proinflammatory cytokines, including IL-1β, IL-6, IL-15, and TNF-α, were significantly increased in sarcopenia patients compared to those in young/healthy volunteers, while the concentrations of two other cytokines, IL-4 and IL-13, were not changed." (PMID 32226296, 2020). "However, our research findings revealed no significant increase in IL-15 levels among patients with sarcopenia compared to the non-sarcopenic controls." (PMID 38032288, 2023). "The area under curve of the ROC analysis to discriminate participants with and those without sarcopenia was 0.65 (95% CI, 0.54-0.75) for TNF-α, 0.74 (95% CI, 0.65-0.84) for IL-1β, 0.80 (95% CI, 0.71-0.88) for IL-6 and 0.55 (95% CI, 0.44-0.66) for IL-15." (PMID 38032288, 2023).